GATA3 (GATA binding protein 3)
Diseases named in the same sentence as GATA3 in open-access papers (continued):
Sharing a sentence is not in itself a finding about the gene and the disease.
tumor (continued). "Our results also suggest that the transcriptional regulation of FOXP3 is controlled by three transcription factors, SMAD3, GATA3, and RUNX3, in a concerted manner involving CNSs and promoter regions of FOXP3 in tumor-induced CD8+ Treg cells." (PMID 28487507, 2017). "With the development of tumor-CD8+ Treg, GATA3 shows reduced affinity towards CNS1 region due to repressive chromatin modification and binds essentially to CNS2 region which displays permissive chromatin modification." (PMID 28487507, 2017). "We further investigated the correlation between GATA3 and HIF-1α expression in the 151 HNSCC tumours by immunohistochemistry, and the results confirmed a significantly positive correlation (Pearson’s correlation coefficient=0.54, P<0.001)." (PMID 28263977, 2017). "Tumours in this cluster show decreased expression of PPAR-γ and GATA3, and significantly increased expression of IFN and antigen presentation pathway genes, in addition to MHC class II genes and those involved in T-cell cytolytic activity." (PMID 29050337, 2017). "The cumulative results show the intricate transcriptional regulation of FOXP3 is controlled by three transcription factors, SMAD3, GATA3, and RUNX3, involving CNSs and promoter regions of FOXP3 in tumor-induced CD8+ Treg cells." (PMID 28487507, 2017). "Results of experimental metastasis models showed that GATA3 overexpression in OEC-M1 and A375 cells significantly increased whereas GATA3 knockdown in OEC-M1 cells significantly decreased lung colonization of tumour cells." (PMID 28263977, 2017). "As we observed a dual role of GATA3 in the regulation of FOXP3 gene expression, we intend to unveil the relative binding of GATA3 in CNS1 and CNS2 region at various stages of CD8+ Treg development in our in vitro tumor model." (PMID 28487507, 2017). "In these GATA3 and HIF-1α double-positive tumours, we further categorized the distribution of positive staining into two types: invasive front and diffuse." (PMID 28263977, 2017). "To improve the usefulness of these markers in the clinic and to determine which cells express GATA, we determined protein expressions of GATA3 and GATA6 on paraffin-embedded tumour samples using standard immunohistochemical techniques." (PMID 29038332, 2017). "High FoxA1 gene expression significantly correlated with high expression of well-established luminal markers, such as GATA3 and ESR1, in primary tumours." (PMID 27045898, 2016). "Recent studies have suggested the existence of at least two subgroups within tumours with an amplification on the HER2-locus, expressing high or low levels of the ESR1, GATA3 and BCL2 gene cluster." (PMID 27341628, 2016). "We revealed TFs whose expression is linked to a large number of tumor-specific enhancers and further characterized selected TFs for each tumor type (e.g., BRCA: GATA3, FOXA1, ESR1, PRAD: HOXC6, DLX1, KIRC: ZNF395) and for specific tumor subgroups." (PMID 27833659, 2016). "Such an observation leads to the hypothesis that mutations in GATA3, although frequent, might not be driver mutations causing tumor progression, because a large tumor size, an irregular tumor shape, and random enhancement texture are usually signs of malignant and aggressive tumors." (PMID 26639025, 2015). "This confirms that FOXA1 and GATA3 expression is commonly and recurrently elevated in the majority of early neoplasias (40/59 cases strong and 15/59 cases intermediate staining for FOXA1; 31/57 cases strong and 21/57 cases intermediate staining for GATA3)." (PMID 24887547, 2014).
tumor (continued). "We observed a noticeable difference of approximately two orders of magnitude in the median relative methylation values detected for GATA3 and GATA5 CGIs in tumor compared to adjacent normal renal tissues." (PMID 24549248, 2014). "Luminal A tumours tend to be low grade tumours that are characterised by over expression of ER-activating genes including LIV1, CCND1, FOXA1, XBP1, GATA3 and Bcl-2." (PMID 24392136, 2014). "Measurements of protein expression by immunohistochemistry on an independent set of early neoplasias confirms that ER pathway regulators FOXA1 and GATA3, as well as ER itself, are consistently upregulated at this early stage." (PMID 24887547, 2014). "Comparison of GATA3 and GATA5 methylation in different tumor cell lines revealed a marker-specific methylation characteristic with high and frequent signals for both methylation marks in RCC lines." (PMID 24549248, 2014). "Among the genes identified in this signature, we noted, consistent with our earlier analyses, GATA3 and MET enrichment in subgroup 10 and 7 tumors, respectively, both of which are known to be preferentially expressed in luminal and basal tumor, respectively." (PMID 21672245, 2011). "By day 7, IFNγ, CSF2, CXCL10, GZMB, PTGS2, TNFα, CD80, CCL22, IL12a, IL13, IL1b, IL6, NOS2, and CTLA4 were significantly upregulated in the tumor-bearing mice bladders and AGTR2 and GATA3 were downregulated." (PMID 22013484, 2011). "An exception is GATA3, which is a target of PRC2 in ES cells but highly expressed in luminal tumours." (PMID 20565864, 2010). "Rather, proliferation of GATA-3-negative stem cell-like cells may cause tumour progression." (PMID 19707195, 2009). "IHC revealed a positivity of the tumor cells for BerEp4, AE1/AE3, GATA‐3, Androgen Receptor (AR, 10%), CAM5.2, Estrogen Receptor (ER, 70%), Ki67 with a score of 10% and Progesterone Receptor (PR, 10%), negativity for TTF‐1, GCDFP‐15, HER‐2, HBME‐1, and Calretinin." (PMID 41239938, 2026). "Notably, GATA3 correlates with hormone receptor (ER/PR) positivity (both 90% in our case), implicating estrogen-response pathways (e.g., ESR1/GREB1) in tumor biology." (PMID 40969274, 2025). "The tumor cells showed strong nuclear expression for GATA3 but no staining for TTF-1, CDX2, and PAX8, inferring primary breast origin." (PMID 40909459, 2025). "GATA3 immunohistochemical stain although non-specific can be expressed in a variety of tumor types; in the appropriate clinical setting, it is helpful for confirming urothelial or mammary origins." (PMID 40860802, 2025). "The histopathological diagnosis and classification of the tumor are based mainly on morphological features and classic immunohistochemical markers (e.g., p63, GATA3, CK5/6, CK20, etc.), while HER2 is not used." (PMID 41155746, 2025). "Additionally, the T‐cell cytotoxic anti‐tumor effector molecule Granzyme B (GZMB) was among the top‐ranked and up‐regulated genes in GATA3‐low tumors." (PMID 41024411, 2025). "Whilst GATA3 mutations are not yet targetable, synthetic lethal interactions between GATA3 and MDM2 in ER + BC supports pharmacological inhibition of MDM2, shown to significantly impair tumour growth in GATA3-deficient models." (PMID 41351070, 2025). "On immunohistochemical (IHC) staining, tumor cells showed patchy expression of CD56, but the tumor was negative for broad-spectrum keratins, PAX8, TTF1, thyroglobulin, calcitonin, HBME-3, CEA, PTH, GATA3, p63, SOX10, and S-100." (PMID 40277780, 2025). "This study revealed a significant difference in GATA3 gene expression between tumor cells (both responders and non-responders) and normal control cells." (PMID 40736702, 2025). "Conversely, most PCLs (84%, 11/13) showed no GATA3 expression and only two cases showed weak intensity of staining in 1% to 25% of tumor nuclei." (PMID 39941848, 2025).
tumor (continued). "Little is reported about potential roles and implications of GATA3 independent of ER, and possible relationships to the BC tumor microenvironment (TME) have not been much explored." (PMID 41024411, 2025). "Following the hypothesis that the tumours with ectopic activation of DNMT3B target the silencing of a number of onco-suppressor genes, primarily GATA3, we performed a GSEA in two different contexts, separately." (PMID 40585280, 2025). "On immunohistochemical analysis, the tumor was positive for synaptophysin, CD56, GATA-3, and S100." (PMID 41179710, 2025). "Immunohistochemically, the tumor cells were positive for GATA-3, CK7, and EMA (apical membranous) while negative for AMACR and CA IX." (PMID 40989704, 2025). "The tumor subtypes reflected by the patient-derived ex vivo cultures were validated by qPCR analysis of keratinization (CNFN, CRNN), basal (KRT5, KRT6), and luminal markers (KRT7, GATA3)." (PMID 41387887, 2025). "By analysing IL1β, IL10, IL18, TNF-α, TLR4, GATA3, and CD68 expression in 50% of PCa HHV-infected FFPE with an elevated inflammation index (61.8%/21), we detected hyper-expressed levels of IL1β, IL18, and TNF-α in the tumour microenvironment." (PMID 40430084, 2025). "The tumor cells stained positive with cytokeratin (CK) 7, and GATA binding protein 3 (GATA3) (a maker of breast origin), while negative with CDX2 (marker of gastrointestinal origin) and TTF1 (marker of lung origin)." (PMID 41025019, 2025). "SCRIPro could accurately predicts well-known master regulators including SPI1, IRF1, FLI1, and STAT2 for mono/macrophages, GATA3, RUNX3, SMARCA4, JUND, and MYB for T-cells, PAX5, BCL2, and IRF4 for B and tumor B-cells." (PMID 39024032, 2024). "Due to its high sensitivity, P63 is recommended as part of a multi-antibody panel (usually along with GATA3, uroplakin II, and high-molecular-weight cytokeratin) in order to establish the urothelial lineage and rule out a secondary tumor to the bladder." (PMID 38534771, 2024). "Moreover, the IHC expression profile (GATA3, CK5/6) of basal/luminal classification from spheroids resembled that of its corresponding parental tumor." (PMID 38435820, 2024). "We noticed that the number of Brca1+/− or Gata3+/− tumor cells, but not the number of Gata3+/+;Brca1+/+ tumor cells, was significantly reduced after OLA treatment." (PMID 38627785, 2024). "OLA treatment of sh-Gata3-Brca1+/+;Gata3+/+ tumor cells, not sh-Ctrl-Brca1+/+;Gata3+/+ tumor cells, again significantly reduced the number of colonies formed." (PMID 38627785, 2024). "Comparing tumor tissues to nontumor tissues, we found a significant downregulation of miR‐1245b‐5p and miR‐92a‐3p and upregulation of GATA3." (PMID 38173189, 2024). "The expression level of miR‐92a‐3p, miR1245b‐5p, and GATA3 were assessed on extracted RNAs of tumor and nontumor tissues from 36 patients with BC using qPCR." (PMID 38173189, 2024). "Hence, other genetic mechanisms of BRCA driver genes, such as GATA3, are likely related to KDM7A-DT’s subtype-specific tumor suppressor functions and require further study." (PMID 38756663, 2024). "All breast-specific markers including SOX10, GATA3, mammoglobin, and GCDFP15, expressing positively at the primary tumor site, may lose their expression at the metastatic site and vice versa." (PMID 38813332, 2024). "Positivity for CK7 (diffuse staining), CAIX (“cup-shaped” expression, with staining of the basolateral but not the luminal portion of tumor cells), GATA3, PAX2, PAX8, 34βE12, AE1/AE3, or CAM5.2." (PMID 38791935, 2024).
tumor (continued). "However, GATA3 (luminal marker) and CK5/6 (basal marker) were significantly correlated with squamous differentiation and high levels of tumor-infiltrating lymphocytes (TILs)." (PMID 39768377, 2024). "We stained the tumor-infiltrating CAR T cells for TCF1, TBET, EOMES, GATA3, ID2, ID3 and IRF4." (PMID 37945901, 2023). "Among them, the target genes of H3K4me3 resulting from FOXA1, GATA3 and PLOR2A as well as H3K27ac resulting from EP300 and GATA3 were significantly enriched in the gene sets (CERES = −2∼−0.4, p < 0.001), signifying a broad dependency for tumor proliferation." (PMID 37876590, 2023). "Herein we have described the sensitivity of high GATA3 expression in non-invasive UC of the urinary bladder and its relation to local recurrence, independent of gender, age, tumor differentiation, and stage." (PMID 37829946, 2023). "Тime to local recurrence did not correspond to tumor grade, gender, age, and GATA3 H-score, but there was a statistically significant correlation between high GATA3 expression and the occurrence of recurrence." (PMID 37829946, 2023). "GATA binding protein 3 (GATA3), E-cadherin and Pax-8 were also present in all neoplasms." (PMID 36816543, 2023). "Immunophenotypically, the tumor was positive for Cytokeratins Oscar and 7, GATA3, GCDFP, HER2, and an androgen receptor but negative for CK20, S100, p40, Melan A, CDX2, TTF1, ER, SATB2, DOG1, synaptophysin, and chromogranin." (PMID 37886914, 2023). "Immunohistochemical results showed that the tumor cells were negative for CK (AE1/AE3), which was positive for residual breast duct epithelium, and GATA3 was negative for tumor cells and positive for residual breast duct epithelium." (PMID 37884941, 2023). "Compared with Cluster1, Cluster2, with poorer prognosis, had chromosomal amplification of various tumor-promoting gene loci, such as E2F3, MYC, and GATA3, and partial or complete deletion of the chromosome where the tumor suppressor gene PTEN and RB1 loci are located." (PMID 37767092, 2023). "In this study, we avoided determining a cut-off rate nor estimating the prognostic value of GATA-3 as the primary endpoint because all BC tumor stages are not represented in this patient material (only pT1-2 tumors)." (PMID 36996051, 2023). "Conversely, c-FOS was readily detected in ER+ and GATA3+ tumor cells, but hardly detectable or weakly expressed in ER− and GATA3 weak or non-detectable tumor cells." (PMID 37353480, 2023). "Unfortunately, high GATA3 expression in class 3 tumours indicates that they should not be regarded as a precursor to MIBC." (PMID 36928373, 2023). "PanTrk and GATA3 were diffusely positive in the nuclei of the tumor cells; mammaglobin, however, was negative in both cases." (PMID 37415052, 2023). "The quantitative real-time polymerase chain reaction (qRT-PCR)-derived “ER gene (ER-ness) score” for the expression of the ESR1 gene and downstream gene targets (ESR1, GATA3, TFF1) was confirmed to be an accurate predictor of the ER status in ER low-status tumor samples." (PMID 36834918, 2023). "To further elucidate the tumor‐suppressive mechanism of MEG3, we predicted transcription factors of the intersecting genes, and confirmed the binding between MEG3 and transcription factor GATA3 in OSCC cells." (PMID 36468944, 2023). "Depletion of Gata3 downregulates c-Fos, activates EMT and enhances tumor-initiating potential." (PMID 37353480, 2023). "In retrospect, the breast tumor first showed a focal area of neuroendocrine features (without positive ER or neuroendocrine staining) while most tumor cells were ER, PR, mammaglobin and GATA3 positive." (PMID 35029184, 2022).
tumor (continued). "In addition to the tumor morphology and documented clinical history, sensitive and specific immunohistochemical (IHC) markers such as GCDFP-15, mammaglobin, and GATA3 are helpful for determining breast origin." (PMID 36284362, 2022). "Using unsupervised hierarchical clustering of six subtyping genes assessed by multiplex RNA hybridization (basal differentiation: KRT5, KRT14, CD44; luminal differentiation: KRT20, GATA3, and FOXA1), 28 tumor samples were each classified as either basal or luminal subtypes." (PMID 36142180, 2022). "More importantly, idasanutlin reduced tumor formation in the context of GATA3-silencing (42 vs 65% treated with DMSO) but not in control (61 vs 56% treated with DMSO)." (PMID 35440675, 2022). "In two of the eight GATA3-negative cases (cases 3 and 9), the GATA3-negative tumor cells were positive for at least one hormone receptor." (PMID 34829389, 2021). "Similar to MYH2, CKM (Muscle type of CK) is down-regulated in tumor (GATA3 mutant and non-mutant) tissues." (PMID 33462316, 2021). "Such GATA3-negative/hormone receptor-positive tumor cells were not limited to any specific architectural pattern, but were randomly dispersed in tubular, ductal, and solid patterns." (PMID 34829389, 2021). "In this study, PAX2 was negative in >95% tumor cells in three cases while GATA3 was negative in >90% tumor cells in all five cases." (PMID 34441384, 2021). "In the absence of GATA3, the metastasis of cancer cells cannot be stopped, and metastatic tumor cells can induce inflammatory responses, stimulate angiogenesis, and acquire nutrients for metastasis." (PMID 34262865, 2021). "Remarkably, Hand2, Phox2b, Gata3 and Isl1 were highly expressed in both TH-MYCN+/+ early hyperplasia and wild-type ganglia at week 1 and remained at this level in both tissues throughout further tumor development." (PMID 34638267, 2021). "We found that DAC drastically enhanced Gata3 expression in p18-/-;Brca1MGKO, but not in p18-/-, tumor cells." (PMID 34373738, 2021). "In addition, PD-1 Ab treatment has been shown to lead to the expansion of a CD8 T-cell cluster in the tumor, expressing Tbet+Eomes+MHCII+BATF+PD-1+TIM-3+CD27+CD69+Gata-3+ that correlated with small tumor size." (PMID 34912335, 2021). "In the current meta-analysis, GATA3 expression was more frequent in tumours from older patients and, although not significant, there was a trend for higher GATA3 expression in males." (PMID 34690921, 2021). "Our data showing a predominance of GATA-3+ Th2 cells, and low numbers of T-bet+ Th1 cells, in NSCLC tumors, are in accordance with a previous report in which cytokines were quantified by ELISA in tumor tissue homogenates." (PMID 34868011, 2021). "BCG-failure tumors were homogeneously GATA3 positive, irrespective of tumor region (MIBC and CIS), but with significantly increased expression levels in TC compared with IC within MIBC (p < 0.0001) and CIS (p < 0.0001)." (PMID 33672843, 2021). "In some microscopic foci, the tumor cells were positive for ER and PR but negative for GATA3 and PAX2, and vice versa." (PMID 34441384, 2021). "We also observed that the luminal marker GATA3 was omnipresent in Ta disease and did not correlate with any specific tumour feature." (PMID 34184816, 2021).